CD74 (CD74 molecule)
Diseases named in the same sentence as CD74 in open-access papers (continued):
Sharing a sentence is not in itself a finding about the gene and the disease.
tumor (continued). "Immunostaining for CD74 in normal tissues and tumor tissues showed an increase in positive CD74 staining in tumor tissues compared to that in normal tissues." (PMID 37629174, 2023). "Within the TME, the tumor homing of mesenchymal stromal cells is regulated by the MIF-(CD74 + CXCR4) ligand–receptor pair in the MIF pathway." (PMID 37874419, 2023). "Our study highlights that tumor-associated fibroblasts (especially FAP + and MFAP5 + fibroblasts) can secrete MIF, which binds to the corresponding receptor CD74 on macrophages to drive immunological escape." (PMID 37344903, 2023). "In conclusion, we determined that CD74, Ki-67, TNM stage, ECOG PS and tumor‐directed treatment were associated with DMPM prognosis." (PMID 37147569, 2023). "Neutrophils in tumour‐invaded TDLN highly expressed AP (CD74 and HLA‐DPA1/DQA1), pro‐angiogenesis (VEGFA) and immunosuppressive (TGFBI)‐related genes." (PMID 37491740, 2023). "As a receptor of inflammatory cytokines, CD74 combines with proinflammatory factors, initiates a signal cascade to promote the formation of tumor lesions." (PMID 37147569, 2023). "Among them, CD74 plays a pivotal role in maintaining tumor homeostasis by releasing a tumor escape signal to inhibit T cell activity." (PMID 37940972, 2023). "TNF-related interactions such as TNF_VSIR and CD74_MIF interactions are enriched in SN, exhibiting more inflammation-related tumor features." (PMID 37745301, 2023). "As examples, MIF-(CD74 + CXCR4) interaction was decreased between tumor and most immune cell types post-treatment." (PMID 36417130, 2023). "We found that tumor cells primarily affected immune cell types via MIF-(CD74 + CXCR4) ligand-receptor pairs." (PMID 38123589, 2023). "To observe the effects of CD74 on tumor growth in vivo, we constructed an orthotopic mouse model in BALB/C nude mice using Capan-1 cells." (PMID 37629174, 2023). "Two subsets of MDSCs expressing different MIF receptors were described: a monocytic MDSC, expressing high levels of CD74, with a large presence within the tumor microenvironment, and a granulocytic MDSC, expressing CXCR2, with a low presence in the tumor." (PMID 36672343, 2023). "Some of these pairs have been reported to have broad functions; for example, CD74-MIF is involved in several biological processes associated with the modulation of inflammation, cardiac function, and tumor formation." (PMID 35912104, 2022). "The presence of CD74 protein on tumour cells membranes and cytoplasm in our study suggests an interaction with macrophage migratory inhibitory factor (MIF) and internalisation of CD74, in agreement with other studies." (PMID 35208514, 2022). "CD74 contributes to tissue inflammation, tumor progression, and metastasis, and most evidence supports a therapeutic role for blocking CD74 in cancer." (PMID 36134665, 2022). "Further analysis showed that ligand-receptor pairs, including MIF − (CD74 + CXCR4), MIF − (CD74 + CD44), MDK–NCL and LGALS9 − CD45, etc. mediated the communication between m6A associated subtypes of TME cells and tumor epithelial cells." (PMID 35509079, 2022). "MIF also triggers TAMs polarization into M2 tumor-promoting phenotypes via CD74 and CXCR7 signal transduction, which not only increases the pro-angiogenic potential of TAMs but also promotes MM cell survival, proliferation, tumor growth and metastasis." (PMID 35842634, 2022). "In concordance with the L-R analysis, the image-based assays indicated the interacting cells mediated by CXCL10/CXCR3 and MIF/CD74 more closely co-localized with each other in tumor tissues as compared to those in NTL tissues." (PMID 35933472, 2022). "We found that a subset of tumor cells expressed HLA-II and that its expression was significantly correlated with that of its chaperone, CD74 (invariant chain) (R = 0.627, p < 0.0001, Pearson correlation)." (PMID 35831288, 2022).
tumor (continued). "Our research suggested the histogenesis and the function of the OCGs in UCOGCP, the TAM enriched characteristics of the TEM, as well as the potential roles of CD74 in this special tumor microenvironment." (PMID 35733218, 2022). "Further in-depth study of each signaling pathway verified that monocytes were directly associated with tumor cells only in the MIF and TNF pathways, in which the most important ligand-receptors were CD74/CD44 and TNF/TNFRSF1B." (PMID 36479092, 2022). "Meanwhile, immunohistochemical analysis showed higher expression of CD74 in metastatic lymph nodes compared with that in the primary tumor." (PMID 36569924, 2022). "We found CAFs which highly expressed CTHRC1 (from F04 and F08) and tumor associated macrophages were mediated by a different set of ligand-receptor pairs, including THY1/aXb2 complex, GRN/TNFRSF1A, CD99/PILRA, CD74/MIF, APP/CD74, ANXA1/FPR1, etc." (PMID 35928443, 2022). "The upregulation of CD74 in many types of cancers suggests its role in facilitating tumour progression and metastasis." (PMID 35208514, 2022). "Immune and stromal cell populations included 2 populations: Macrophages 1 (c1: C1qa, C1qb, C3aR1, Cd68, Csf1r, Tlr2, and Cd86) and 2 (c6 + c9: Ccr7, Csf2rb, Il1b, and Cd74) expanded in PNs as a percentage of total tumor cells." (PMID 36134665, 2022). "Twelve of the samples showed marked overexpression of CD74 in tumor cells (black arrow indicates tumor cells), with essentially cytoplasmic and membrane staining (black arrow indicates membrane staining)." (PMID 34944801, 2021). "Labeling with HPA010592, an antibody against CD74, showed higher intensity in the tumor tissue than that in normal tissue." (PMID 33854546, 2021). "Mechanistically, Mif-containing tumor cells regulate angiogenic gene expression via a MIF/CD74/MAPK axis in vitro." (PMID 33542244, 2021). "The results from the TIMER resource also indicated that CD74 expression was inversely correlated with tumor purity." (PMID 34944801, 2021). "Some studies also support the CD74 involvement in the prevention of the EMT process in other tumor histotypes." (PMID 34968251, 2021). "The macrophage migration inhibitory factor (MIF) receptor CD74 is overexpressed in various neoplasms, mainly in hematologic tumors, and currently investigated in clinical studies." (PMID 34671548, 2021). "Repotrectinib inhibited proliferation of Ba/F3 cells in vitro, and tumor volumes were decreased in mice expressing Ba/F3 Cd74–Ros1-WT or Cd74-Ros1-G2032R xenograft tumors." (PMID 34680353, 2021). "Based on an IHC-based study, CD74 was also detected in tumor-infiltrating lymphocytes, also correlating with a statistically significantly better prognosis." (PMID 33925387, 2021). "In lymphoid tissues far away from tumor cell areas expression of the immune-related gene CD74 was observed while in tissues in close proximity to tumor cell areas, expression of the immune-related gene IGLL5 was seen." (PMID 35008286, 2021). "ENT treatment led to increased expression of ciita, tap1, tap2, cd74, and major histocompatibility genes—involved in antigen processing and presentation—suggesting an increased ability to T cells to engage tumor cells, consistent with previous reports." (PMID 33369199, 2021). "Several genes of antiviral immune response pathways such as HLA-B, HLA-C, HLA-DQB1 IFI6, IFITM3, CD74, and tumor suppressor genes EFEMP1 and EGR1, are upregulated in tumor and downregulated in TAS." (PMID 34316327, 2021). "Due to the small amount of cell sample used to detect the methylation pattern of CD74, and OS tumours are highly heterogeneous, our results need to be further verified with clinical samples to obtain more accurate results." (PMID 34957096, 2021). "CD74 was highly expressed in the low-purity tumor, which indicated a relatively high proportion of stromal and immune cells (p < 0.05)." (PMID 34540893, 2021).
tumor (continued). "As IFNγ is secreted by macrophages and CD4+ and CD8+ T lymphocytes in the tumor microenvironment, it was conceivable that CD74 overexpression in solid tumors, and prognostic value, is simply a reflection of the level of immune infiltration." (PMID 34944801, 2021). "Next, we investigated how the 3 key populations of DB-CRCs (CD8+GzB+, CD8+Ki67+, and CD68+CD74+ cells) were distributed across regions of the same tumor." (PMID 34197832, 2021). "Immunostaining of CD74 was scored in two different ways: only considering immunoreactivity in tumor cells or in the entirety of the tissue section (with an H-score)." (PMID 34944801, 2021). "In brain metastatic tumor cells, the highly expressed CD74 promotes the normal processing mechanism of HLA-II and binding of complex HLA peptides, which is crucial for improving the prognosis of patients." (PMID 33159014, 2020). "In parallel, elevated levels of Cd74 and Arg1 RNA in tumor microglia was also detected at the protein expression level of CD74 and ARG1 protein." (PMID 32299465, 2020). "We moreover analyzed and found that CD74 expression correlated with higher levels of MHC class II expression by tumor cells and with a dense TIL response." (PMID 33327409, 2020). "We found that the monocytic subset of MDSCs (M-MDSCs) expressed high levels of the MIF cognate receptor CD74 and was localized in the tumor microenvironment." (PMID 32625208, 2020). "We currently envision that tumor CD74 functions in antigen presentation to the immune cells in the tumor microenvironment rather than acting as a receptor for an inflammatory protein MIF." (PMID 33327409, 2020). "Funtionally, the CD74+ microglia/macrophages were shown to reduce the secretion of IFN-γ in the tumor microenvironment, which would contribute to established an immunosuppressed niche." (PMID 31244853, 2019). "Several studies reported overexpression of MIF and CD74 in multiple cancers and that the MIF/CD74 signaling pathway promotes tumor progression and angiogenesis." (PMID 31866994, 2019). "Nevertheless, we detected significantly reduced beta-values in CD74high versus CD74low protein expressors, indicating a potential epigenetic regulation of CD74 expression in tumor cells from BM." (PMID 29490700, 2018). "CD74 tumor cell expression was heterogeneous among all investigated entities with highest expression levels in BM of RCC and NSCLC (mean H-Score of 133.9 and 73.2) respectively." (PMID 29490700, 2018). "In a first step, we assessed protein expression profiles of CD74 in BM from distinct primary tumor entities." (PMID 29490700, 2018). "In summary, our results demonstrate that a functional HLA class II processing machinery in brain metastatic tumor cells, reflected by a high expression of CD74 and a complex tumor cell HLA peptidome, seems to be crucial for better patient prognosis." (PMID 29490700, 2018). "To further assess heterogeneous CD74 expression patterns among the same tumor entity we investigated a potential epigenetic regulation of CD74 expression in BM." (PMID 29490700, 2018). "We analyzed CD74 and HLA class II expression on tumor cells in a subset of 236 human brain metastases, primary tumors and peripheral metastases of different entities in association with clinical data including overall survival." (PMID 29490700, 2018). "Although the expression of these molecules is not prognostic for BM and e.g. resected NSCLC, we investigated the association of PD-1/CD8 positive TILs as well as PD-L1 positive tumor cells with CD74 in BM." (PMID 29490700, 2018). "Expression of CD74 within tumor cells showed a predominantly cytoplasmic staining pattern with weak membrane staining visible in occasional cells, and was heterogeneous within positive staining tumors." (PMID 27058619, 2017). "CD74 and CD44 were observed to accumulate in cytoplasmic compartments, suggesting they associate with each other to facilitate tumour growth and metastasis." (PMID 29190904, 2017).
tumor (continued). "In a previous study, we showed that adhesion of tumour cells on the reconstituted membrane matrix Matrigel increases when CD74 and CD44 are overexpressed." (PMID 29190904, 2017). "The expression of CD74 in neoplastic tumour cells was heterogeneous, ranging from strong cytoplasmic and membranous (samples C4 and C5) to weak granular cytoplasmic (sample C3)." (PMID 28114961, 2017). "Our results therefore suggest that the anti tumor effect predicted to be exerted by CD74's role in facilitating the immune response is dominant over the protumor effect involving MIF signal transduction, expected from laboratory studies on MIF." (PMID 27058619, 2017). "In summary, in MPM cell lines, activated MIF/CD74 pathway has a pro-tumorigenic function by increasing tumor cell proliferation and protecting them from apoptosis." (PMID 26883190, 2016). "Subsequent studies have shown that CD74 is highly expressed in various types of tumor cells and has multiple roles in a variety of biological processes." (PMID 27626171, 2016). "In the future, in order to clarify the complex role of MIF and/or CD74 from tumor and stromal cells in MPM development, we plan to perform i.pl." (PMID 26883190, 2016). "Our findings showed an increased extent of MIF expression in cancer cells and in stromal fibroblasts of BC tumor, in contrast to a less uniform increase of CD74 expression mainly in stromal lymphocytes, macrophages and endothelium." (PMID 24939415, 2014). "CD74 expression has been shown in solid tumors and has been connected with poor prognosis and tumor progression." (PMID 23572149, 2013). "CD74 is an integral membrane protein acting as a signaling molecule adjuvant and is involved in the mechanism of tumor cell survival." (PMID 23572149, 2013). "In all cases, CD74 expression was reported as a prognostic factor reflecting tumor progression and poor clinical prognosis." (PMID 23572149, 2013). "In summary, the molecular analyses of end-stage tumor tissues with integrations in Cd74 suggest a more complex scenario of Cd74 function in B-cell tumors than oncogenic over-expression or lack of tumor suppressor function." (PMID 20416035, 2010). "The Cd74 mRNA levels in tumor tissue harboring integration in the Cd74 locus were assessed by Northern blot hybridizations in order to analyze possible effects of the integrated proviruses on Cd74 expression pattern in the MLV-induced B-lymphomas." (PMID 20416035, 2010). "Apart from any disturbance imposed by the alternative isoform itself, any changes in canonical Cd74 activity due to its putative association with the novel isoform could be envisioned to disturb the fine-tuned balance of immune surveillance mechanisms holding a tumor at bay." (PMID 20416035, 2010). "While additional work is needed to elucidate the biological significance of these proteins, CD24 and CD74 expressed only in small proportion of cells indicating tumor heterogeneity and subtypes of tumor initiating cells (CD24+/CD44+) present in HNSCC." (PMID 19602232, 2009). "Tumor-derived lactateinhibits CD74 transcription via C/EBPα acetylation." (PMID 41804723, 2026). "Interestingly, recent studies have reported CD74 overexpression in human tumor-infiltrating regulatory T cells (Tregs), suggesting a possible role in modulating the immunosuppressive compartment of the TME." (PMID 41597203, 2026). "However, recent studies implicate CD74 as a broader regulator of tumor–immune interactions, modulating antigen presentation, cytokine signaling, and immune evasion across diverse cancers." (PMID 41597203, 2026). "On the other hand, SCs express TLRs to recognize tumor alarm signals and carry antigen‐presenting markers such as CD74/CD1a, which may participate in innate immune activation and antigen presentation." (PMID 41583906, 2026).
tumor (continued). "Binding of MIF to CD74 initiates the intracellular signaling cascades that promote cell proliferation, survival, and resistance to apoptosis hallmarks of malignant transformation that tumor cells readily exploit." (PMID 41597203, 2026). "Tumor-intrinsic CD74 has been documented in a broad spectrum of malignancies." (PMID 41597203, 2026). "Additionally, RNA m6A methylation-associated cellular subpopulations within the TME and tumor epithelial cells can participate in many and comprehensive interactions through ligand-receptor pairings, such as MIF-(CD74+CD44)." (PMID 40842994, 2025). "Furthermore, studies have shown that CD74 can be rapidly internalized on tumor cells, making it a determining factor for conjugated chemotherapy or radioisotope carriers." (PMID 40470045, 2025). "Interestingly, gene CD74 was overexpressed in NSCLC in most of the studies; however, with the results of our analysis of the TCGA-LUSC dataset, the expression of CD74 was significantly decreased in the tumor samples." (PMID 40136480, 2025). "On dividing cells into SSR4-positive and -negative groups, CellChat analysis indicated that SSR4 may regulate the interactions that existed between ESCC tumor plasma cells and the tumor microenvironment (TME) by modulating the MIF/CD74/CXCR4 axis." (PMID 40066443, 2025). "Activation of CD74 via MIF is related to tumour growth and might mediate effects on proliferation in islet macrophages." (PMID 39508880, 2025). "Notably, co-expression analysis of LAMP1 with tumor markers CD74 and CD68 revealed that LAMP1 expression is mainly located within the tumoral area, potentially representing cancer cells, CAFs, and MDSCs." (PMID 40872517, 2025). "CD74 primarily promotes tumour progression through its signalling function, making it a potential tumour marker or targeted drug target Due to the absence of targeted inhibitors for CD74, the MIF inhibitor ISO‐1 was chosen to inhibit CD74 function by occupying the binding domain of MIF." (PMID 40411322, 2025). "Additionally, upregulation of antigen presentation genes including H2-Aa, H2-Ab1, H2-Eb1, Tapbp and Cd74 as well as Stat1 and Cxcl9 - a chemokine that recruits immune cells to the tumor, was observed in the CAR-T group." (PMID 40568084, 2025). "Additionally, GSVA analysis demonstrated the activation of multiple tumor pathways in the CD74 low expression group." (PMID 40470045, 2025). "For confirmation, MSC-associated protein levels of CD74 and SOX2 in tumor tissues were examined." (PMID 39940960, 2025). "The presence of MIF in the tumor microenvironment likely binds to CD74 on apCAFs." (PMID 39891284, 2025). "Regardless of the tumor type, the mutation frequencies of CD74, FGFR1, and RET were significantly greater in patients with NRG1 fusion than in patients without NRG1 fusion." (PMID 40730881, 2025). "APP-CD74 interactions may be involved in immune regulation, and studies have shown that CD74 plays a key role in antigen presentation and its aberrant expression may promote tumor immune escape through the NF-κB pathway." (PMID 41180476, 2025). "Moreover, we further analyzed the mRNA levels of Cd74 and Cxcr4 in tumor tissues of the mouse Hepa1‐6 implantation models." (PMID 40018995, 2025). "In view of the advantages of radiomics, this study used radiomics techniques to predict CD74 mRNA expression in NSCLC tumor tissues and combined them with bioinformatics analysis to explore the molecular mechanism of the tumor immune response related to CD74 expression." (PMID 40470045, 2025). "Spatial omics data revealed that CD74 downregulation in malignant cells correlates with invasive progression, while macrophage‐enriched regions exhibit active MIF‒CD74 interactions in preinvasive components, suggesting a potential role for immune‒malignant crosstalk in tumour progression." (PMID 40847563, 2025). "Importantly, tumour regions with strong positive CD74 expression showed significantly lower LSD1 expression than those with weak CD74 expression." (PMID 40356247, 2025).